NF2 (NF2, moesin-ezrin-radixin like (MERLIN) tumor suppressor)
Diseases named in the same sentence as NF2 in open-access papers (continued):
Sharing a sentence is not in itself a finding about the gene and the disease.
schwannomatosis (continued). "NF1 is the most common of the three conditions, with a frequency of 1 in 2500–3000 live births, whereas NF2 and schwannomatosis are considerably less common." (PMID 30382390, 2018). "Lastly, the large gap in precise genetic diagnoses in these conditions is highlighted with no pathogenic mutation identified in a considerable number of people who were clinically labelled as having NF2 or schwannomatosis." (PMID 30382390, 2018). "As of October 14, 2015, 4476 living U.S. patients with a confirmed diagnosis of NF1, NF2, or schwannomatosis were enrolled in the patient registry." (PMID 30157837, 2018). "Schwannomatosis is partially explained by mutations in the SMARCB1 gene, located 6 Mb centromeric to the NF2 gene at 22q11.23." (PMID 25739810, 2015). "Fifty two of 1254 NF1 patients developed MPNST, with MPNST also occurring in 2/181 cases of schwannomatosis and 2/895 NF2 patients." (PMID 23036231, 2012). "Plexiform tumors were found in all three groups, more commonly in NF1 patients (40%) than in NF2 and schwannomatosis patients (18% and 14%, respectively) (p = 0.01)." (PMID 22558206, 2012). "We performed an international multicenter study of WBMRI to assess tumor burden of internal nerve sheath tumors in NF1, NF2, and schwannomatosis." (PMID 22558206, 2012). "NF2-related Schwannomatosis (NF2-SWN) remains a disorder with few effective treatment options." (PMID 41595145, 2026). "Segmental schwannomatosis has been seen in approximately one third of non-NF2-related schwannomatosis, but these cases have not generally been associated with identifiable SMARCB1 or LZTR1 mosaic variants." (PMID 41284083, 2025). "Moreover, we reported novel related gene mutations in the exon sequencing results of patients with 7 cases of familial NF2-related schwannomatosis." (PMID 41209567, 2025). "Patients with NF2-related schwannomatosis had an even distribution of samples with either two distinct NF2 variants or one NF2 variant and LOH of chromosome 22 (44%), whereas patients with uVS predominantly possessed one NF2 variant with LOH (53–59%)." (PMID 39941762, 2025). "However, there are xenograft mouse models with human NF2-related schwannomatosis tumors in the sciatic nerve of nude mice." (PMID 40940747, 2025). "Therefore, the expectation is that few young patients with uVS actually harbored NF2-related schwannomatosis." (PMID 39941762, 2025). "In summary, the consensus among clinicians was that a 3D volumetric analysis and visualization tool could greatly benefit the treatment of NF2-related schwannomatosis, but it must be implemented with caution." (PMID 40737523, 2025). "Some affected individuals, particularly at younger ages, who met older criteria for schwannomatosis without a VS had a mosaic NF2 pathogenic variant." (PMID 41160189, 2025). "Among these, the plexiform variant is exceedingly rare, with only four reported cases, none of which were associated with NF2 or schwannomatosis." (PMID 41236587, 2025). "Thus, while bevacizumab demonstrates positive effects on hearing, tumor control, and symptomatology in NF2-related schwannomatosis, careful consideration of potential side effects is crucial." (PMID 38672561, 2024). "Therefore, long term outcome in patients with sporadic IES is expected to be better than in NF2-related schwannomatosis." (PMID 38992191, 2024). "Primary IES in NF2-related schwannomatosis appears to be extremely rare." (PMID 38992191, 2024). "Based on their molecular characteristics, NF is classified into NF1, NF2, and schwannomatosis." (PMID 39157066, 2024). "Only bevacizumab, an anti-angiogenic agent, has been shown to limit growth in a subset of NF2-related schwannomatosis patients, but not without the risk of significant side effects." (PMID 38216553, 2024).
schwannomatosis (continued). "When comparing clinical data across the different NF2 groups, we found that age distribution differed significantly, with the lowest median age (15.1 years) in patients with NF2-related schwannomatosis and the highest median age (54.0 years) in patients with NF2 mutations detected in the tumor." (PMID 38265489, 2024). "Patients with schwannomatosis develop tumors harboring independent somatic pathogenic variants in the NF2 gene which are not present in their constitutional DNA." (PMID 36440500, 2023). "Importantly, there were no robust significant differences in signalling pathways, gene expression, cell type abundance or imaging mass cytometry staining between NF2-related schwannomatosis and sporadic vestibular schwannoma." (PMID 37680691, 2023). "There are three types of NF: NF1, NF2, and schwannomatosis (SWN)." (PMID 36971896, 2023). "However, differences between NF2-related schwannomatosis and the more common sporadic disease include NF2-related schwannomatosis patients presenting an increased number of tumours, multiple tumour types and younger age at diagnosis." (PMID 37680691, 2023). "While for NF2, a cumulative lesion pattern with an increasing number of peripheral nerve lesions from proximal to distal was described, in schwannomatosis, the maximum extent of nerve lesions is present at the mid-thigh level, with a marked decrease towards the distal site." (PMID 35453828, 2022). "While NF2-PNP is predominantly characterized by an axonal loss with an additional, but less pronounced, demyelination and consecutive sensory and motor deficiencies, the most common symptom of schwannomatosis is local, multifocal of diffuse pain." (PMID 35453828, 2022). "NF2 and schwannomatosis are more difficult to diagnose and distinguish clinically." (PMID 35698239, 2022). "Besides bilateral vestibular schwannoma as the hallmark of NF2, DRG hyperplasia has further been confirmed as a highly accurate and easily investigable pathognomonic marker in the discrimination to schwannomatosis as the third neurofibromatosis subtype." (PMID 34652463, 2022). "For 5/13 tumors, all from the same individual, no other germline PVs in other schwannomatosis genes were identified and no somatic NF2 variants were identified in 4/5 tumors resected from this patient." (PMID 35723634, 2022). "As peripheral nerve lesions in schwannomatosis are morphologically comparable to those found in patients with NF2, a further discriminatory pattern might exist." (PMID 35453828, 2022). "Unlike NF2, schwannomatosis patients with germline loss of SMARCB1 have a higher risk of developing MPNSTs." (PMID 34604034, 2021). "NF2 and schwannomatosis are rare diseases, and patients may be difficult to recruit to clinical trials unless the drugs are effective and well tolerated." (PMID 34604034, 2021). "The molecular mechanisms by which inactivation of the LZTR1 or SMARCB1/INI1 gene in addition to the NF2 gene causes schwannomatosis are not understood." (PMID 34604034, 2021). "Additionally, the impact of barriers to successful employment across NF1, NF2 and Schwannomatosis populations should be considered, given each presentation of the corresponding diseases are inherently different." (PMID 34020694, 2021). "There are three types in NF: NF1, NF2, and schwannomatosis (SWN)." (PMID 34072574, 2021). "The most common form is NF1 (96%), followed by NF2 (3%) and the lesser known form schwannomatosis." (PMID 33767727, 2021). "The work on NF2 and schwannomatosis is presented in another paper." (PMID 34012067, 2021). "Nine children bore a sporadic tumour without underlying phacomatosis (11%), 8 had NF2 (9.8%) and 2 schwannomatosis (2.4%), A total of 168 surgical interventions were performed, and 206 tumours were removed." (PMID 32506255, 2020). "Therefore, the possibility of evolution towards generalized schwannomatosis or even NF2 cannot be excluded for all patients." (PMID 31438995, 2019).
schwannomatosis (continued). "In this month’s journal club we review two articles relating to these conditions: a study providing insights into the epidemiology of schwannomatosis and NF2, and a phase 1 study examining the use of a selective inhibitor of mitogen-activated protein kinase (MAPK)." (PMID 30382390, 2018). "A total of 1192 patients met criteria for NF2 and 399 for schwannomatosis." (PMID 30382390, 2018). "While NF2 and schwannomatosis are lower prevalence conditions than NF1, and so resources may be expected to be fewer for these patients, concerns for equity of access to healthcare necessitate attention to these disorders." (PMID 30157837, 2018). "Birth incidence was 1:27,965 for NF2 and 1:68,956 for schwannomatosis." (PMID 30382390, 2018). "Despite the clinical overlap with neurofibromatosis type 2 (NF2), schwannomatosis is not caused by germline NF2 gene mutations." (PMID 27921248, 2017). "For example, a multimodal approach including a relaxation response resiliency program (3RP) has been recently used in a pilot study involving patients with NF1, NF2, and schwannomatosis, with encouraging results in terms of coping strategies and quality of life." (PMID 25884655, 2015). "Although most schwannomatosis cases are sporadic, instances of autosomal dominant transmission with incomplete penetrance have also been reported, though linkage analysis has now excluded the NF2 locus, suggesting schwannomatosis is a distinct entity." (PMID 22937797, 2012). "However, schwannomatosis is often genetically heterogeneous, and the NF2 gene mutation is not always involved." (PMID 40940747, 2025). "Similar to the situation in schwannomatosis patients, the loss of both Smarcb1 and Nf2 did not increase the malignancy of the tumours in mGFAP-Cre; Smarcb1flox/flox;Nf2flox/flox mice as compared to tumours in mGFAP-Cre; Nf2flox/flox mice with biallelic Nf2 loss but retention of Smarcb1 activity." (PMID 40794298, 2025). "Schwannomatosis not related to NF2 can result from mutations in tumor suppressor genes on chromosome 22 including but not limited to the SWI/SNF-related BAF chromatin remodeling complex subunit B1 (SMARCB1) and leucine zipper like post-translational regulator 1 (LZTR1 genes; Tamura, 2021)." (PMID 41001135, 2025). "In addition to functional differences associated with NF2 versions lacking exons 2–3, several patient-derived NF2 related-schwannomatosis NF2 missense mutations within the N-terminal FERM domain were found which impaired NF2 interactions with DCAF1." (PMID 37280085, 2023). "Thus, is seems that in both NF2 and schwannomatosis, there is a direct link between the occurrence and number of these tiny nerve lesions, while secondary processes nearby may be responsible for the development of PNP symptoms." (PMID 35453828, 2022). "Currently, there are no drugs approved for NF2-associated tumors or schwannomatosis." (PMID 35291225, 2022). "The true incidence of schwannomatosis is unknown but thought to be similar to NF2." (PMID 34604034, 2021). "SMARCB1, LZTR1, and NF2 clearly function as classical tumour suppressor genes, and hence, it is not unreasonable to suppose that other schwannomatosis predisposition genes might also act in an onco-suppressive manner." (PMID 27921248, 2017). "Similar to schwannomatosis patients, loss of both Smarcb1 and Nf2 does not increase the malignancy of mGFAP-Cre;Smarcb1flox/flox;Nf2flox/flox tumors compared to mGFAP-Cre;Nf2flox/flox tumors with single Nf2 loss." (PMID 28824165, 2017). "Schwannomatosis patients also do not harbor germline mutations in the merlin gene, NF2." (PMID 26657314, 2015). "Recent research revealed considerable overlap between NF2-SWN and classic non-nf2-related schwannomatosis (non-NF2-SWN), suggesting a continuum within a broader spectrum of schwannomatosis-related disorders." (PMID 40510571, 2025).
schwannomatosis (continued). "Notably, PFS differed significantly between patients with tumors harboring NF2 mutations that were only detected in the tumor and patients with SP-EPN with no NF2 mutation detected (p = 0.009) as well as between cases with no NF2 mutation detected and NF2-related schwannomatosis patients (p = 0.02)." (PMID 38265489, 2024). "Neurofibromatoses (NF; including NF1, NF2, and schwannomatosis) are a group of rare neurogenetic disorders (NF1 occurs in approximately 1:2700 live births; NF2 and schwannomatosis occurs in approximately 1:25,000–33,000 life births, respectively)." (PMID 37213775, 2022). "The predominant model of inheritance for familial non‐NF2‐related schwannomatosis is a dominant model, similar to that of NF1 and NF2‐related schwannomatosis." (PMID 35723634, 2022). "Four of the 13 patients underwent germline genetic testing (31%): 2/2 patients with suspected schwannomatosis, 2/11 patients with clinically diagnosed NF1; including the patient that met clinical criteria for both NF1 and NF2." (PMID 35698239, 2022). "Although some NF2 patients also show a reduced IENFD, the extent is less pronounced than in schwannomatosis." (PMID 35453828, 2022). "Schwannomatosis is less common, less well studied, and less well understood compared to NF1 and NF2." (PMID 34885143, 2021). "Additionally, incorporation of molecular criteria has been proposed, including detection of NF2 gene variants in the peripheral blood or in multiple tumors, and exclusion of patients with lesions harboring mutations in LZTR1 which are associated with schwannomatosis." (PMID 31161239, 2020). "We observed a high prevalence of nerve sheath tumors in schwannomatosis patients (71%), NF1 patients (60%), and NF2 patients (42%)." (PMID 22558206, 2012). "This case highlights schwannomatosis as a rare, painful condition distinct from NF1 and NF2." (PMID 41970298, 2026). "The important feature to distinguish non-NF2-related schwannomatosis is the absence of other NF2-SWN-related tumours such as intradermal schwannoma and ependymoma or ophthalmic features." (PMID 41160189, 2025). "Our case emphasizes the necessity of considering schwannomatosis in individuals who present with multiple schwannomas, even when typical NF2 characteristics are not present." (PMID 40337438, 2025). "Standard clinical features of Schwannomatosis include multiple schwannomas, chronic pain, numbness, tingling, or weakness in the affected areas, with less frequent skin manifestations than NF1 and NF2." (PMID 40764996, 2025). "Unlike NF1 and NF2, Schwannomatosis primarily affects the peripheral nervous system and is characterized by chronic pain and neurological deficits." (PMID 40764996, 2025). "In NF2-related schwannomatosis, constitutional frameshift and nonsense (truncating) variants are linked to an aggressive phenotype originating at an adolescent age." (PMID 39941762, 2025). "Whole-exome sequencing with the genomic DNA from peripheral blood leukocytes showed that patient 1 with INF2 p.Gly73Asp had no germline, schwannomatosis-related gene variants including 22q loss of heterozygosity (LOH), NF1, NF2, LZTR1, SMARCB1, and COQ6." (PMID 39857711, 2025). "Prior attempts to characterize potential blood biomarkers have focused on NF2-related schwannomatosis rather than the more common sporadic VS, which comprises >90% of cases and had limited sample sizes (<30 patients)." (PMID 37948527, 2023). "Other common features of NF2 such as ependymomas and ocular features such as retinal hamartoma, epiretinal folds and juvenile cataracts have not been reported in schwannomatosis." (PMID 35361920, 2022). "In this study, we performed extended genetic screening of 75 unrelated schwannomatosis patients without identified germline PVs in NF2, LZTR1, or SMARCB1." (PMID 35723634, 2022). "The reason why grouped areas of Schwann cell proliferations arise nearby sensory neurons in NF2, but not in schwannomatosis, still remains obscure." (PMID 34652463, 2022).
schwannomatosis (continued). "With only one FDA-approved therapy for NF1, no approved therapies for NF2 or schwannomatosis, and significant limitations to conventional therapeutic options in general, novel agents are greatly needed." (PMID 34885143, 2021). "Apart from the expected excess of VS in people with NF2, they also had significantly more non-vestibular cranial schwannomas than people with schwannomatosis." (PMID 30382390, 2018). "The characteristic presentation of schwannomatosis is with chronic pain associated with cutaneous and central schwannomas, but without the other features of NF1 or NF2." (PMID 30382390, 2018). "Germline mutations in LZTR1, a gene closely linked to NF2 and SMARCB1 on chromosome 22, have recently been identified in a significant proportion of schwannomatosis patients lacking SMARCB1 germline mutations." (PMID 28824165, 2017). "There is a phenotypic overlap among patients that are mosaic NF2 and patients with sporadic Schwannomatosis, consisting of the presence of multiple non-vestibular nerve schwannomas." (PMID 25739810, 2015). "Internal tumors were more common in schwannomatosis patients (71%) than in NF2 patients (45%) (p = 0.01); the prevalence in NF1 patients (60%) was not significantly different than either schwannomatosis or NF2 patients (p>0.05)." (PMID 22558206, 2012). "Unlike NF1 and NF2, Schwannomatosis primarily affects the peripheral nervous system." (PMID 40764996, 2025). "Moreover, known VS predisposing conditions, NF2-related schwannomatosis and LZTR1-related schwannomatosis, were not used as exclusionary criteria for cases." (PMID 36546557, 2023). "Strikingly, while many NF2 patients may suffer from sensorymotor neuropathy, individuals affected by schwannomatosis do not." (PMID 32443592, 2020). "Finally, one patient (Family ID 219) with a clinical diagnosis of Schwannomatosis and negative for mutations in NF2, LZTR1, and SMARCB1 is under investigation for a somatic mosaicism in NF2." (PMID 31370276, 2019). "Some studies were not conclusive; others suggested either NF2 or Schwannomatosis." (PMID 25739810, 2015). "Exploration of the possible interactions of potential candidate genes for schwannomatosis with the known causative genes, might provide some insight into the type and location of novel PVs in cases where no variants in SMARCB1, LZTR1, or NF2 have been identified." (PMID 35723634, 2022). "Consequently, the genetic diagnosis of this patient was mosaic NF2 rather than schwannomatosis." (PMID 27921248, 2017). "Consequently, 27% of sporadic schwannomatosis patients who do not exhibit germline NF2, SMARCB1, and LZTR1 mutations, but who do display tumour-specific biallelic NF2 inactivation, could, in principle, be caused by mutations in hitherto unidentified gene(s)." (PMID 27921248, 2017). "Multiple biopsies of different sites at different time periods were consistent with histology that confirmed the diagnosis of schwannomatosis, with no NF1 or NF2 features." (PMID 41970298, 2026). "Schwannomatosis is the rarest form of NF, with a prevalence that is not well established but is believed to be less common than NF1 and NF2." (PMID 40764996, 2025). "In many studies assessing the clinical symptoms of patients with schwannomatosis (SWN), no strict distinction was made between LZTR1-related or SMARCB1-related or any other type of non-NF2-related SWN." (PMID 40794298, 2025).